HP (haptoglobin)
Diseases named in the same sentence as HP in open-access papers (continued):
Sharing a sentence is not in itself a finding about the gene and the disease.
colitis (5 papers, 2011 to 2025). Inflammation of the colon. "To date, handful evidences have revealed potential immunoregulatory targets of 2′‐FL in protecting against experimental IBD, our results indicated that haptoglobin and serpina3n were involved in the pharmacological function of 2′‐FL in attenuating colitis." (PMID 40501496, 2025). "The significantly elevated plasma haptoglobin and intraluminal mediators accompanied with higher NF-κB/IκBα ratio indicated that experimental colitis was active." (PMID 24416230, 2014). "Haptoglobin is an acute-phase protein, which is used as a marker of systemic inflammation to monitor disease activity in experimental colitis in rodent models." (PMID 24416230, 2014). "Haptoglobin, a critical DEP that was significantly elevated in DSS‐induced colitis and reduced by 2′‐FL administration in the present research, is an acute phase protein with antimicrobial activity." (PMID 40501496, 2025). "Of note, alpha-1-B glycoprotein (A1BG) was also decreased, whereas haptoglobin (HP), pregnancy zone protein (PZP), and hemopexin (HPX) were increased throughout the colitis progression in IL-10−/− mice." (PMID 30774653, 2019).
diabetic nephropathy (5 papers, 2012 to 2022). "There is a need to determine if the haptoglobin is associated with an increased risk for the development of diabetic nephropathy in a larger group of dogs at various stages of diabetic nephropathy." (PMID 35327145, 2022). "Urine haptoglobin (uHP) level prospectively predicts diabetic kidney disease (DKD) progression." (PMID 29572449, 2018).
Fever (5 papers, 2012 to 2025). Body temperature elevated above the normal range. "On the other hand, piglets in the Gps + HP-PRRSV2 and HP-PRRSV2 alone groups had fever following HP-PRRSV2 infection (rectal temperature ≥ 40 °C)." (PMID 37235448, 2023). "Fever and serum haptoglobin are acute-phase responses induced by a variety of cytokines, including IL-1, IL-6 and IFN-γ." (PMID 22435642, 2012).
ischemic stroke (5 papers, 2015 to 2022). A stroke disorder caused by obstruction of blood flow to the brain, due to thrombotic (local blood clot formation) or embolic (due to a blood clot or other material traveling from another site) event. "For example, haptoglobin and serum amyloid-A overexpression have been associated with atherothrombotic ischemic stroke, as studied by matrix-assisted laser desorption/ionization-time-of-flight (MALDI-TOF) mass spectrometry (MS)." (PMID 33265898, 2020). "It has been suggested that the expression level of haptoglobin can be employed as a biomarker for atherothrombotic ischemic stroke diagnosis since it is high upon the occurrence of ischemia‐reperfusion injury." (PMID 34018701, 2021). "Our data suggest that the aging systemic milieu plays a critical role in functional recovery after ischemic stroke, and elucidates a previously unrecognized role for haptoglobin in the prognosis of ischemic stroke." (PMID 28966798, 2017). "Using a proteomic approach, we found that haptoglobin levels were significantly increased in serum of aged rats and that intraperitoneal administration of haptoglobin impaired outcome after ischemic stroke in young rats." (PMID 28966798, 2017). "Thus, levels of haptoglobin and serum amyloid A can be considered as biomarkers to predict atherothrombotic ischemic stroke as opposed to cardioembolic stroke." (PMID 33265898, 2020).
Neonatal sepsis (5 papers, 2011 to 2025). Systemic inflammatory response to infection in newborn babies. "Proteomics mapping of cord blood identifies haptoglobin “switch-on” pattern as biomarker of early-onset neonatal sepsis in preterm newborns." (PMID 40964021, 2025). "Recent studies have demonstrated that novel biomarkers, such as resistin, haptoglobin, and sTREM-1, could be applied for clinical prognostic identification of neonatal sepsis, but their expensive and time-consuming disadvantage hinders widespread implication in neonatal sepsis." (PMID 40687411, 2025). "Additionally, elevated cord blood haptoglobin level could serve as a predictor for neonatal sepsis." (PMID 41346634, 2025).
Nephropathy (5 papers, 2018 to 2024). A nonspecific term referring to disease or damage of the kidneys. "Haptoglobin (Hp), an acute-phase response protein secreted by the liver, functions to modulate renal iron loading and prevent kidney damage by releasing iron." (PMID 37759769, 2023). "The data identified haptoglobin (HPT) and α-1-microglobulin/bikunin precursor (AMBP) as two biomarkers with the highest ability to distinguish between healthy individuals and patients with nephropathy, and between diabetic patients with and without DN." (PMID 30486327, 2018).
non-alcoholic steatohepatitis (5 papers, 2013 to 2025). "Recent findings indicate that the haptoglobin 2 allele is linked to a histological response to vitamin E treatment in patients with metabolic dysfunction-associated steatohepatitis (MASH)." (PMID 39860434, 2025). "Differential quantitation analysis revealed that five N-glycopeptides at sites N184 and N241 of serum haptoglobin bearing a monofucosylated triantennary glycan were significantly elevated during the progression from non-alcoholic steatohepatitis (NASH) and cirrhosis to HCC." (PMID 33562077, 2021). "For instance, the increased fucosylation level or different fucosylation forms in α-1-acid glycoprotein 1 (AGP1) and haptoglobin (HPT) could differentiate nonalcoholic steatohepatitis, cirrhosis from healthy controls, or nonalcoholic steatohepatitis from nonalcoholic fatty liver disease." (PMID 40821120, 2025).
Pancytopenia (5 papers, 2009 to 2025). An abnormal reduction in numbers of all blood cell types (red blood cells, white blood cells, and platelets). "The patient presented with profound pancytopenia and biochemical signs of intramedullary haemolysis, significantly raised LDH, indirect hyperbilirubinaemia, and undetectable haptoglobin, consistent with ineffective haematopoiesis." (PMID 41487850, 2025).
preeclampsia (5 papers, 2013 to 2021). Preeclampsia is a hypertensive disorder of pregnancy that is characterized by new-onset hypertension with proteinuria presenting after 20 weeks of gestation, and depending on mild or severe forms may initially present with severe headache, visual disturbances, and hyperreflexia. "Study 1: Haptoglobin polymorphism and susceptibility for the development of preeclampsia." (PMID 25101128, 2014). "Our previous study shows that HP is downregulated in placenta and plasma of women with preeclampsia." (PMID 33969702, 2021). "Changes in plasmatic haptoglobin have been proposed as a biomarker of preeclampsia." (PMID 30005082, 2018). "In pregnant women, its role as a diagnostic marker of preeclampsia (PE) and of fetal and maternal outcomes was evaluated, but even if lower haptoglobin levels were associated with PE occurrence, it was not possible to define it as biomarker for pregnancy complications." (PMID 30005082, 2018).
pulmonary hypertension (5 papers, 2017 to 2025). Increased pressure within the pulmonary circulation due to lung or heart disorder. "Here, we identified 532 DEPs; several of these DEPs may be critical to CMS or pulmonary hypertension, including α-1-acid glycoprotein, collagen, fibulin, haptoglobin, PLTP, and TAGLN2." (PMID 34471201, 2021). "This relationship between CRP and pulmonary hypertension was supported by the results of another study, which also evaluated haptoglobin, albumin and PON-1, and confirmed the relationship between pulmonary hypertension and acute phase response, especially in the positive APP CRP and haptoglobin." (PMID 29143665, 2017).
schizophrenia (5 papers, 2013 to 2021). A major psychotic disorder characterized by abnormalities in the perception or expression of reality. "Serum results revealed that Haptoglobin and Plasma protease C1 inhibitor were significantly upregulated in first-onset schizophrenia patients (corrected P < 0.05)." (PMID 29249827, 2017). "By example, imputed genotypes of polymorphic SVs at the major histocompatibility complex (MHC) and haptoglobin (HP) loci in large populations have demonstrated disease relevance for schizophrenia and untoward cardiovascular lipid phenotypes, respectively." (PMID 28260531, 2017). "The analytes showing the largest ratiometric differences included ferritin, macrophage migration inhibitory factor, carcinoembryonic antigen and haptoglobin, which were all more than 1.5-fold higher in schizophrenia patients compared to controls." (PMID 24244349, 2013).
vitamin B12 deficiency (5 papers, 2009 to 2025). A disease characterized by low serum levels of vitamin B12, either inherited or acquired. "Hemolytic anemia from vitamin B12 deficiency has classic hemolysis lab findings such as elevated LDH, low haptoglobin, elevated indirect bilirubin, and schistocytes seen on the peripheral smear, as seen in the presented patient." (PMID 40400815, 2025). "Vitamin B12 deficiency can present with a hemolytic picture in 1.5% of patients with elevated LDH, low haptoglobin, and elevated indirect bilirubin mostly due to ineffective erythropoiesis and intramedullary destruction." (PMID 27559485, 2016).
adenoma (4 papers, 2020 to 2025). A neoplasm arising from the epithelium. "A protein panel, consisting of haptoglobin (Hp), LAMP1, SYNE2, and ANXA6, was identified for the detection of high‐risk adenomas (sensitivity of 53% at specificity of 95%)." (PMID 31784980, 2020). "Stool fibrinogen, MMP-8, MMP-9, PGRP-S, haptoglobin, and myeloperoxidase emerge as promising biomarkers for distinguishing CRC/advanced adenomas/healthy stools, meeting or outperforming current yardsticks." (PMID 41033463, 2025). "Comparing CRC to adenoma samples, some blood particles were still upregulated in CRC patients with CP, HP, and SERPINA3 displaying the largest difference." (PMID 36369736, 2022).
alcoholic liver diseases (4 papers, 2014 to 2023). A disorder caused by damage to the liver parenchyma due to alcohol consumption. "The most important alterations observed in alcoholic liver disease are desialylation of transferrin and also haptoglobin, alpha 1-antitrypsin, and ceruloplasmin." (PMID 24959592, 2014). "Abnormal glycan structures of liver‐derived proteins such as transferrin (TF) and haptoglobin have been described in alcoholic liver disease, nonalcoholic steatohepatitis and primary sclerosing cholangitis." (PMID 32557671, 2020).
aspergillosis (4 papers, 2017 to 2024). Aspergillosis is an infection, growth, or allergic response caused by the Aspergillus fungus. "Other factors influencing the haptoglobin concentrations in the present study could have been the exclusion of dogs with additional diseases and the lower number of dogs with aspergillosis (3 dogs compared to the 13 dogs in the cited study)." (PMID 39409857, 2024). "In another study using high resolution capillary electrophoresis and mass spectrometry methods, several changes in acute phase proteins including fibrinogen and haptoglobin, as well as lipoproteins, were identified in the plasma of an African penguin with confirmed aspergillosis." (PMID 35928207, 2022). "However, quails infected with fungal infection (aspergillosis) were found to have lower haptoglobin levels compared to the uninfected groups." (PMID 35477136, 2022). "Likewise, broiler chickens infected by bronchitis virus showed significantly higher haptoglobin than healthy individuals, whereas Japanese quails (Coturnix japonica) infected by aspergillosis had a lower haptoglobin concentration than control birds." (PMID 28070333, 2017).
Autoimmunity (4 papers, 2011 to 2026). The occurrence of an immune reaction against the organism's own cells or tissues. "HP expression increases in patients with various inflammatory and autoimmune disorders, including systemic lupus erythematosus and rheumatoid arthritis." (PMID 41498512, 2026). "It has been suggested that Haptoglobin plays a modulatory and protective role on autoimmune inflammation of the CNS." (PMID 21696593, 2011).
bacteremia (4 papers, 2014 to 2025). "The diagnostic performance of Lpc-2 in predicting bacteremia was higher in younger children (aged <13.9 months) after adjustment for stunting (AUC, 86%), whereas haptoglobin performed better in older children (>13.9 months) regardless of nutritional status." (PMID 24696240, 2014). "The antibacterial activity, reactive oxygen species production, and antibacterial mechanisms of derived haptoglobin-conjugated gold nanoclusters were confirmed by culturing the bacterium Escherichia coli with hemoglobin to simulate bacteremia." (PMID 36296784, 2022). "Our work demonstrated derived haptoglobin-conjugated gold nanoclusters as a promising nanoantibiotic for combating bacteremia." (PMID 36296784, 2022). "Haptoglobin (Hp) improves immune‐tolerance via suppressing the proinflammatory mediators and plays a role in preventing bacterial proliferation during bacteremia." (PMID 35040515, 2022).
chronic hepatitis C (4 papers, 2014 to 2026). "(2013) for chronic hepatitis C patients included variables such as hyaluronic acid, TGF-β1, α2-macroglobulin, Matrix Metalloproteinase (MMP)-2, apolipoprotein-A1, urea, MMP-1, alpha-fetoprotein, haptoglobin, red blood cell count, hemoglobin, and TIMP-1." (PMID 41551471, 2026).
chronic kidney disease (4 papers, 2013 to 2025). Impairment of the renal function secondary to chronic kidney damage persisting for three or more months. "In 2012, the patient was admitted to our intensive care unit with end-stage renal disease, malignant hypertension, and pulmonary edema, and laboratory results consistent with TMA (platelet count 109 G/l, LDH 1,136 U/l, and haptoglobin not detectable)." (PMID 29321782, 2017).
cognitive decline (4 papers, 2021 to 2025). "Our proteomic results were in accordance with human AD studies, and the comparison showed increased haptoglobin and prothrombin in the plasma of AD patients, indicating an increased risk for cognitive decline and deterioration." (PMID 33514370, 2021). "Our group has shown that the haptoglobin genotype is related to cognitive decline and to hippocampal volume in older adults with T2D." (PMID 40338932, 2025). "Furthermore, our prior findings relating haptoglobin to cognitive decline focused on Jewish and African American participants; along with the results on Japanese older adults, the association of haptoglobin glycosylation with T2D-related cognitive decline may generalize across races and ethnicities." (PMID 40338932, 2025).
endothelial dysfunction (4 papers, 2016 to 2025). In vascular diseases, endothelial dysfunction is a systemic pathological state of the endothelium (the inner lining of blood vessels) and can be broadly defined as an imbalance between vasodilating and vasoconstricting substances produced by (or acting on) the endothelium. "Previous studies have shown that intravascular hemolysis promotes endothelial dysfunction associated with reduced eNOS activity in SCD mice, whereas haptoglobin preserves the NO signaling pathway in arteries during hemolysis." (PMID 36176769, 2022).
Huntington disease (4 papers, 2011 to 2021). Huntington disease (HD) is a rare neurodegenerative disorder of the central nervous system characterized by unwanted choreatic movements, behavioral and psychiatric disturbances and dementia. "Similarly, altered expression of the hemoglobin scavenger haptoglobin was shown in AD, PD and Huntington’s disease (HD)." (PMID 30231533, 2018).
hyperadrenocorticism (4 papers, 2022 to 2025). "Haptoglobin levels, which are elevated in hyperadrenocorticism, were found to decrease significantly following trilostane treatment, indicating potential benefits for systemic inflammatory markers." (PMID 39943185, 2025). "Likewise, serum haptoglobin concentrations decreased in dogs with treated hyperadrenocorticism, but were still elevated, potentially due to poor control of hyperadrenocorticism, cortisol precursors, or secondary effects of hyperadrenocorticism." (PMID 35448526, 2022). "However, haptoglobin levels can be influenced by the administration of corticosteroids to dogs, and increased haptoglobin levels are often observed after corticosteroid therapy and in spontaneous hyperadrenocorticism." (PMID 37146011, 2023).
intracerebral haemorrhage (4 papers, 2021 to 2026). "We aimed to investigate the association of Haptoglobin (Hp) phenotypes with perihematomal edema (PHE) and neurological outcomes after intracerebral hemorrhage (ICH)." (PMID 35888091, 2022). "The expression of HP was found increased after intracerebral haemorrhage in vivo, which could prevent haemoglobin‐induced neuronal ferroptosis is as an antioxidant." (PMID 33528895, 2021).
leukopenia (4 papers, 2014 to 2023). "Repeat labs revealed leukopenia with 51% bands, hemoglobin 11.0 g/dL down from 13.9 g/dL, platelets 74 K/μL trending down to 15 K/μL, PT 23.5 sec., aPTT 60.3 sec., D-dimer greater than 20 μg/mL, fibrinogen 190 mg/dL, LDH 1515 IU/L, haptoglobin less than 20 mg/dL, and creatinine 1.84 mg/dL." (PMID 38152150, 2023).
macrocytic anemia (4 papers, 2020 to 2026). Anemia that is characterized by increased red blood cell volume. "We report a 78-year-old woman who presented with fatigue, macrocytic anemia, reticulocytosis, elevated lactate dehydrogenase, low haptoglobin, indirect hyperbilirubinemia, a direct antiglobulin test positive for C3 and negative for IgG, and a cold agglutinin titer of 1:320." (PMID 42110104, 2026).
mental disorder (4 papers, 2020 to 2026). A disease that has its basis in the disruption of mental process. "We identified four key genes and their downstream pathways, specifically QDPR, DBI, MAX and HP genes, linking the mental disorders and susceptibility to the development of IBD." (PMID 40118833, 2025). "Gene-based association tests for the 42 DNV-bearing genes implicated haptoglobin (HP) and pyruvate carboxylase (PC), 2 brain-expressed genes associated across 3 psychiatric disorders that carry potentially pathogenic DNVs." (PMID 32383744, 2020). "By integrating evidence from multi-omics perspectives, we identified four mental disorder-related genes: QDPR (Tier 1), DBI (Tier 1), MAX (Tier 3) and HP (Tier 3) as prior regulatory genes in the pathogenic pathway of IBD and its subtypes." (PMID 40118833, 2025). "We identified four mental disorder-related genes, i.e., QDPR, DBI, MAX and HP and their downstream pathways that played crucial role in the susceptibility of IBD and UC, suggesting their potential as intervention and therapeutic targets for gut-brain axis diseases in the future." (PMID 40118833, 2025). "Three of the five studies included in this systematic review demonstrate an association between increased serum zonulin levels and impaired intestinal barrier function in mental disorders, i.e., in ADHD and ASD, and one study on increased plasma haptoglobin levels and impaired IP." (PMID 32635367, 2020).
peritonitis (4 papers, 2013 to 2023). Inflammation of the peritoneum (tissue that lines the abdominal wall and covers most of the organs in the abdomen). "Similarly, other studies have shown an increase in fibrinogen and haptoglobin in the peritoneal fluid of horses with peritonitis." (PMID 36417417, 2022).
pulmonary tuberculosis (4 papers, 2009 to 2026). A bacterial infection that affects the lungs and is caused by Mycobacterium tuberculosis. "Independent ELISA validation similarly showed that HP was significantly upregulated in pulmonary TB patients compared with HC." (PMID 41477556, 2026).